ITGAL (integrin subunit alpha L)
Diseases named in the same sentence as ITGAL in open-access papers (continued):
Sharing a sentence is not in itself a finding about the gene and the disease.
tumor (continued). "In addition, gene set enrichment analysis (GSEA) revealed cell activation involved in the immune response in ITGAL‐expressing cells versus other cells in tumours." (PMID 38613346, 2024). "Interestingly, we found that ITGAL expression was significantly positively related to the tumor-infiltrating lymphocytes (TILs), immune inhibitor, immunostimulator, MHC molecule, chemokines as well as its receptors." (PMID 37256932, 2023). "In some LUSCs, ITGAL expression was present in lymphoid aggregates and tumor necrosis." (PMID 37835514, 2023). "To further clarify the function of ITGAL in the immune microenvironment, we uncover that ITGAL level was positively related to the immune modulator, including the tumor-infiltrating lymphocytes (TILs), immune inhibitor, immunostimulator, MHC molecule, chemokines as well as its receptors." (PMID 37256932, 2023). "This study uncovered the critical involvement of ITGAL in GC and the possible connection and mechanism by which ITGAL may regulate tumor-infiltrating immune cells." (PMID 35399517, 2022). "In AML patients, ITGAL expression was extremely increased in tumor tissues." (PMID 35999614, 2022). "ITGAL, the counterreceptor-ligand of ICAM1, was expressed in immune cells surrounding the tumor cells, both in the periphery and central tumor, as well as in the tumor-associated TLS." (PMID 30082828, 2018). "CD2 and ITGAL could mediate cell adhesion between immune cells and other types of cells and trigger cytotoxic function against tumor." (PMID 30333226, 2018). "Furthermore, our findings may provide a targeted anti-tumor strategy for ITGAL by influencing the tumor immune microenvironment." (PMID 39605903, 2024). "It appears that ITGAL may function as a tumor suppressor in NSCLC." (PMID 38646528, 2024). "Therefore, ITGAL may play a greater role in regulating immune cell function in the tumor microenvironment." (PMID 38646528, 2024). "However, the possible mechanisms of ITGAL about tumor development and immune engagement with GC are still unknown." (PMID 35399517, 2022). "However, the possible function of ITGAL in regulating tumor immunity and its clinical significance in GC are still unknown." (PMID 35399517, 2022). "Notably, a recent study discovered that ITGAL expression was positively correlated with M1 macrophage infiltration and negatively correlated with M2 macrophage infiltration across various cancers, indicating its pivotal role in the tumor immune microenvironment." (PMID 40718439, 2025). "Integrin alpha L (ITGAL) is a member of the integrin family, confirmed to affect the tumor immune microenvironment." (PMID 40718439, 2025). "Specifically, the expressions of CXCL10, ICMA1, IL18, ITGAL, SOCS3, and TLR3 were higher in tumor tissues compared to their corresponding paracancerous tissues." (PMID 40838069, 2025). "Our findings demonstrated a significant correlation between ITGAL expression and NK cells in LUAD, suggesting their involvement in immune response‐related cell activation within tumours." (PMID 38613346, 2024). "ITGAL is a prognostic biomarker for LUAD patients, and it exhibits a dual function in LUAD by not only suppressing the malignant progression of tumour cells but also modulating immunotherapy through NK cells." (PMID 38613346, 2024). "The stromal expressions of ITGAL and ITGAX, together with tumor expression of TMEM119 in NSCLC, were demonstrated." (PMID 37835514, 2023). "A genetic reduction in microglia recruitment, identified by ITGAL/CD11A markers, has been shown to delay tumor onset." (PMID 37830595, 2023). "Our research has particularly highlighted the role of ITGAL in modulating CD8+ T cell activity through glycosylation, opening avenues for the development of targeted therapies to enhance anti-tumor immunity." (PMID 37901252, 2023).
tumor (continued). "Comparing top DEGs which differentiate dura-originating from tumor-originating T cells, dura T cells’ DEGs were related to T cell migration and function, such as CXCR3 and ITGAL, as well as cell motility genes SUSD3 and FGD3." (PMID 35534852, 2022). "As expected, integrins interacting with ECM components are expressed in a cell‐type‐selective fashion, such as ITGA4, ITGAL and ITGB7 by immune cells, while tumour and stromal cells strongly expressed ITGA3, ITGAV and ITGB1/4/5/6/8." (PMID 34841720, 2021). "Conversely, ITGAL and ITGAM were strongly decreased in LMNA+ cells and this is in accordance with the anti-tumour effects reported in the literature for these two integrins." (PMID 34680461, 2021). "These sites were annotated to genes involved in diverse biological pathways, including neurological development (AHNAK, PGAP3), lymphocytic function (ITGAL), apoptosis (RELT), tumor suppression (ZGPAT), and endothelial-to-mesenchymal transition (PRSS23)." (PMID 32084330, 2020). "Furthermore, mIF results indicated that the patients with ITGAL-high expression tend had significantly higher CD8+ T cells, CD68+ macrophages, CD4+ T cells, and CD20+ B cells infiltration in their tumor tissues." (PMID 38646528, 2024). "In spite of this, the possible mechanisms of ITGAL on tumor development and immune interaction with NSCLC are still unknown, and experimental studies addressing the correlation between ITGAL and immune cell infiltration are limited." (PMID 38646528, 2024). "During our analysis of 35 tumors, we identified a noteworthy negative correlation between the ITGAL expression and tumor purity." (PMID 39605903, 2024). "The results of the present study suggest that lipid-soluble statins may exert anti-tumour effects not only by interfering with HMGCR, but also, possibly, by inhibiting ITGAL." (PMID 38651149, 2024). "Both TIGIT and CD96 inhibit NK and T cell function via binding to CD226, indicating a possibility that ITGAL may suppress NK and CD8+ T cell’s killing activities of tumor cells." (PMID 37835514, 2023). "Furthermore, the Tumor Immune Estimation Resource (TIMER) and immunohistochemistry were performed to investigate the relationship of ITGAL with immune-related cells in the distinct tumor microenvironments." (PMID 35399517, 2022). "In addition, immunohistochemical staining for ITGAL and multiplex immunofluorescence (mIF) staining for ITGAL, CD20, CD68, CD4, and CD8 from tissue microarrays containing 118 tumor tissues and paired paracancerous tissues from patients with NSCLC were performed." (PMID 38646528, 2024). "Moreover, TECs also interacted with T/NK cells via ICAM1/ICAM2-(ITGAL + ITGB2), which might contribute to immune cell infiltration and effective anti-tumor immune response." (PMID 39093451, 2024). "The differential expressions of ITGAL in human tumors and the clinical prognosis in GC were systematically analyzed via multiple databases including Gene Expression Profiling Interaction Analysis (GEPIA), UALCAN, Tumor Immune Estimation Resource (TIMER), and Kaplan–Meier (KM) plotter." (PMID 35399517, 2022). "Second, the functional role of ITGAL in LUAD and its molecular mechanism within the tumour microenvironment have not been validated through in vivo experiments." (PMID 38613346, 2024). "By taking advantage of the protein expression data within the Human Protein Atlas, we observed a general presence of ITGAL and ITGAX in the stromal compartment but not in tumor cells in both LUAD and LUSC." (PMID 37835514, 2023). "On the other hand, Itgal, Itgax, and Tmem119 in LL2 tumors were downregulated by taxifolin; their human counterparts (ITGAL, ITGAX, and TMEM119) displayed positive T cell dysfunction values, suggesting their negative impact on CTL-derived cytotoxicity in tumor cells." (PMID 37835514, 2023).
tumor (continued). "ITGAL, GBP1, GBP2 and ITGB2 were all upregulated in TLS positive tumors compared to TLS negative, but no changes could be observed in Tumor versus Normal and TLS positive versus Normal." (PMID 30082828, 2018).
infection (61 papers, 2009 to 2025). The state of being infected such as from the introduction of a foreign agent such as serum, vaccine, antigenic substance or organism. "ITGAL encodes integrin alpha L, a protein involved in immune cell adhesion and migration, which can influence antiviral responses and recruitment of immune cells to infection sites." (PMID 40927453, 2025). "The ITGAL gene encodes the integrin alpha L chain, and loss of function variants in this gene have been associated with compromised immunity including increased susceptibility to infection to Salmonella in mice." (PMID 35073835, 2022). "Together, the greater abundance of ITGAL, CD44, and CX3CR1 after calving suggested a potential greater influx and adhesion of leukocytes into tissues, likely contributing to decrease the incidence of infection postpartum." (PMID 32260288, 2020). "The membrane glycoprotein LFA-1, an integrin which is composed of the integrin alpha L chain ITGAL (CD11) and the beta 2 chain ITGB2 (CD18) is expressed on T-cells, were it functions in recruitment of the cells to the site of infection and interacts with antigen-presenting cells." (PMID 29453458, 2018). "Thus ITGAL expression may be regulated by LMP1 and the EBNAs in a temporal fashion during infection." (PMID 24068937, 2013).
cancer (30 papers, 2014 to 2025). A tumor composed of atypical neoplastic, often pleomorphic cells that invade other tissues. "Specifically, we found that CTNNB1 mutated carcinomas showed significantly downregulated levels of ITGAL, ITGAM, and ITGB2, which are involved in leukocyte transendothelial migration." (PMID 41227323, 2025). "ITGAL showed prognostic significance in pan-cancer patients, correlated with clinical features, and associated with specific signaling pathways." (PMID 39605903, 2024). "The GSEA algorithm analysis was carried out in pan-cancer to elucidate the underlying physiological processes that might be mediated by ITGAL and subsequently, six tumors with similar results were selected." (PMID 39605903, 2024). "Meanwhile, low ITGAL expression is associated with cancer stage, age, and overall event in NSCLC." (PMID 37256932, 2023). "Conversely, ITGAL acted as a protective factor in six cancer types, namely CESC, LUAD, LARC, HNSCC, SKCM-P, SKCM, and SKCM-M." (PMID 39605903, 2024). "Initially, we evaluated three immune scores, namely StromalScore, ImmuneScore, and EstimateScore, to determine their correlation with ITGAL in pan-cancer." (PMID 39605903, 2024). "The objective of this research is to evaluate the correlation between ITGAL expression and prognosis in various cancer types, as well as the impact on the immune microenvironment." (PMID 39605903, 2024). "In our study, we undertook a thorough analysis to investigate the potential correlation between ITGAL expression and 60 genes related the immune checkpoint pathway in diverse cancer types." (PMID 39605903, 2024). "Our study comprehensively analyzed ITGAL expression across various cancers, validated by Immunochemistry (IHC) in the laboratory." (PMID 39605903, 2024). "We discovered that the expression of ITGAL in cancer tissues and paracancerous tissues is different in most cancer types, except UCEC, COAD, COADREAD, PCPG, CHOL." (PMID 39605903, 2024). "Contralaterally, M2 showed high invasion in two cancer types with low ITGAL expression, indicating a good prognosis." (PMID 39605903, 2024). "ITGAL and ITGB2 are associated with carcinogenesis and immune regulation, and are considered prognostic biomarkers for various cancers." (PMID 39684926, 2024). "The study investigated the relationship between DNAss and ITGAL in different types of cancer, specifically LGG, UVM, LUAD, SKCM, and HNSCC." (PMID 39605903, 2024). "Across various cancer types, the expression of ITGAL showed predominantly positive correlations with both TMB and MSI." (PMID 39605903, 2024). "In briefly, ITGAL acts as a pan-oncogene and displays distinct expression patterns in different types of cancer." (PMID 39605903, 2024). "By conducting survival analysis in four domains—Overall Survival (OS), Disease-Specific Survival (DSS), Progression-Free Survival (PFS), and Disease-Free Survival (DFS)—we discovered the prognostic significance of ITGAL across various cancer types." (PMID 39605903, 2024). "We also examined the relationship between ITGAL expression and diverse drug sensitivity in the cancer therapeutics response portal database." (PMID 37256932, 2023). "ITGAL is a member of the integrin family which the dysregulation and is correlated with cancer progression and immune response." (PMID 37256932, 2023). "ITGAL expression in lymph node stage samples was markedly higher in lymph nodes at all stages of cancer development than normal, indicating that ITGAL is present in malignancy." (PMID 35399517, 2022). "Sample type, subgroup, cancer stage, lymphatic node stage, and worse survival were strongly related to high ITGAL expression." (PMID 35399517, 2022). "We discovered that ITGAL was an aberrant expression between cancer and paracancerous tissues in various malignancies." (PMID 35399517, 2022). "Integrin subunit alpha L (ITGAL) was found aberrantly expressed in multiple cancer types, suggesting its essential role in tumorigenesis." (PMID 35999614, 2022).
cancer (continued). "ITGAL combined with other five peripheral blood derived genes has been used to predicate OS in cancer patients." (PMID 34633989, 2021). "Differential expression of ITGAL in cancer and adjacent normal tissues." (PMID 39605903, 2024). "Further, some studies indicate that ITGAL might play a key role in cancer growth and transformation, making it a potentially useful target in the treatment of a wide variety of cancers." (PMID 38646528, 2024). "Based on this study, we speculate that in KIPAN and UVM, ITGAL also increases the migration and invasion ability of cancer cells by affecting certain regulatory genes." (PMID 39605903, 2024). "The immune cells such as CD8+T cells and activated CD4 memory cells had high infiltration in cancers where higher expression levels of ITGAL indicated good prognosis, while low CD8+ T cells’ infiltration was observed in two cancer types where high ITGAL expression was linked to poor prognosis." (PMID 39605903, 2024). "It was found that ITGAL participated in pan-cancer immune regulation-related pathways, particularly in leukocyte-mediated cytotoxicity, lymphocyte-mediated immunity, adaptive immune response, cytokine signaling in the immune system, and antigen processing and presentation." (PMID 39605903, 2024). "These researchers suggested that ITGAL might have a significant influence on cancer growth and transformation, and may be a novel target in treating a variety of malignancies." (PMID 35399517, 2022). "Although leukocyte adhesion and migration are closely-related to humoral immune response, function of ITGAL in cancer immune-oncology remains unclear." (PMID 31227749, 2019). "ITGAL might exert an important function in the growth and transformation of cancer." (PMID 39605903, 2024). "Our findings indicated a strong positive correlation between ITGAL and these immune scores, indicating that ITGAL expression significantly contributes to the enhancement of immunity, which may be the reason why some cancers have a better prognosis, such as HNSCC, LUAD and SKCM." (PMID 39605903, 2024). "Moreover, we clearly show that ITGAL expression represses the progression of LUAD cancer cells." (PMID 38613346, 2024). "External validation yielded a 4-gene set (GZMK, GZMA, ITGAL, and IL7R); higher gene expression levels predicted better overall survival in The Cancer Genome Atlas cohort (p=0.005)." (PMID 40766148, 2025). "The ITGAL knockdown counteracted KMT2D-mediated M1 macrophage polarization and its anti-cancer effects on NSCLC." (PMID 40718439, 2025). "Inhibition of ITGAL abrogated KMT2D overexpression-mediated M1 macrophage polarization and its anti-cancer effects on NSCLC." (PMID 40718439, 2025). "Of note, consistent with the co-amplification profile of ITGAD, ITGAL, ITGAX, and ITGAM, we observed similar dysregulation patterns for them in cancers (belonging to one sub-cluster), validating our analytic pipeline." (PMID 39436262, 2024). "The study focused on investigating the role of ITGAL in the TME, its relationship with immune infiltration in different cancer types." (PMID 39605903, 2024). "ICAM-1 on target cells binds to its cognate receptor LFA-1 (ITGAL/ITGB2) on effector lymphocytes (e.g., CTLs and NK cells), strengthening the interaction between the cytotoxic killer cells and carcinoma target cells." (PMID 35572601, 2022). "Another important mechanism that we identified among the LR biomarkers is the stimulation of LFA-1 (encoded by ITGAL and ITGB2 genes) by ICAM (ICAM2 → ITGAL, ICAM1_ICAM3 → ITGAL, and ICAM3 → ITGB2 in 18, 11, and 8 cancer types, respectively)." (PMID 34430923, 2021). "Methylation of ITGAL and ANPEP were down-regulated, while methylation of CD69 and PTPRC were up-regulated in cancer." (PMID 34633989, 2021). "Furthermore, a Univariate Cox regression model was employed to investigate the correlation between ITGAL expression and Progression-Free Survival (PFS) in various cancer types." (PMID 39605903, 2024).
cancer (continued). "B4GALT3 might be suppressing cancer immunity by synthesizing the glycan structure of molecules on the CD8+ T cell surface, as evidenced by the changes in the glycan structure of ITGAL in immune cells." (PMID 37901252, 2023). "In addition, ITGAL, ITGAX, and TMEM119 were also strongly correlated with macrophages and other immune cell populations in LUAD and LUSC as well as across a panel of human cancer types." (PMID 37835514, 2023).
ITGAL also shares sentences with these, for which no sentence is quoted: malaria (5 papers); Sepsis (5); Arthritis (4); rheumatoid arthritis (4); bacterial infections (3); colitis (3); Stroke (3); systemic sclerosis (3); Airway obstruction (2); clear-cell renal cell carcinoma (2); Crohn disease (2); inflammation (2); influenza (2); migraine (2); multiple sclerosis (2); plaque psoriasis (2); pneumonia (2); preeclampsia (2); psoriatic arthritis (2); scleroderma (2); thyroid cancer (2); ulcerative colitis (2); abortion (1); acute renal failure (1); acute respiratory distress syndrome (1); adenocarcinoma (1); allergic asthma (1); amyotrophic lateral sclerosis (1); and Muscular Disorder (1); atopic asthma (1).
A further 72 diseases each share a sentence with ITGAL in 1 paper.